MYO7A (myosin VIIA)
Diseases named in the same sentence as MYO7A in open-access papers (continued):
Sharing a sentence is not in itself a finding about the gene and the disease.
deafness (continued). "Since patient USHsrf40 didn’t have a vestibular problem, a phenotype observed in both USH I and III type patients, it is possible that the two mutations in MYO7A in USHsrf40 only lead to deafness while mutations in CGNA1 are the underlying cause of the RP phenotype." (PMID 26338283, 2015). "Combining the targeted capture of 131 known deafness genes, next-generation sequencing, and bioinformatic analysis, we identified two deleterious compound heterozygous mutations in the MYO7A gene: a reported missense mutation c.73G>A (p.G25R) and a novel nonsense mutation c.462C>A (p.C154X)." (PMID 25080338, 2014). "MYO7A is associated with deafness and other neurosensory disorders based on OMIM." (PMID 23597238, 2013). "We undertook a comprehensive ENU mouse screen at the Australian Phenomics Facility (APF) to identify and characterise novel mouse models of recessively inherited hearing loss and present data on two novel mouse models of deafness with mutations in the Myo7a gene." (PMID 23251483, 2012). "We have now identified MYO7A as a key deafness gene among the indigenous sub-Saharan African populations from the Limpopo Province of South Africa." (PMID 33671976, 2021). "Several reported Myo7a deafness mutants that mapped to the surface of MF2 were shown to disrupt harmonin binding, revealing the molecular basis for the disruption of the tripartite complex assembly and of mechanotransduction." (PMID 33671976, 2021). "For example, patients U597, U1241, U1486 and U1809 who carry two MYO7A missense alterations present with a typical USH1 phenotype with profound deafness and RP occurring in the second decade of life." (PMID 34948090, 2021). "As summarized above, in this study, rare pathogenic variants were identified in four separate deafness-associated genes, TECTA, MYO7A, HGF, and POU3F4, which have distinct expression profiles and functions in the inner ear." (PMID 33976695, 2021). "In this study, we performed targeted NGS in three Pakistani consanguineous families and identified novel variants in TECTA and POU3F4 and previously reported variants in MYO7A and HGF as the pathogenic causes for prelingual, severe-to-profound deafness." (PMID 33976695, 2021). "As well as USH, two forms of non-syndromic HL and deafness, DFNB2 and DFNA11, are associated with MYO7A mutations." (PMID 33193648, 2020). "Recent comprehensive next‐generation sequencing (NGS) analysis has helped clarify genetic epidemiology; i.e., GJB2 is the predominant deafness‐causing gene, with the other common genes being CDH23, SLC26A4, MYO15A, COL11A2, and MYO7A." (PMID 32027099, 2020). "Targeted NGS of 127 hearing loss‐related genes was carried out in the 9 probands, which allowed us to detect 5 reported and 5 novel variants in 6 distinct deafness genes including CDH23, GIPC3, MYO7A, TRIOBP, TECTA, and OTOF." (PMID 32864763, 2020). "The use of inherited disease genes sequencing panel identified the causative and novel variants in deafness related genes (GJB2, MYO7A, CDH23, TH and EVC2) in deaf brothers." (PMID 30881389, 2019). "It is concluded that in addition to novel mutations in MYO7A, TH and EVC2, the CDH23 and GJB2 can also be responsible for deafness in the family with consanguineous marriages." (PMID 30881389, 2019). "In the current study, we detected one reported and six novel mutations in 5 distinct deafness genes (TRIOBP, LHFPL5, CDH23, PCDH15, and MYO7A) in 5 recessive families." (PMID 29568747, 2018). "Several Myo7a deafness mutants that map to the surface of MF2 disrupt harmonin binding, revealing the molecular basis for how they impact the formation of the tripartite complex and disrupt mechanotransduction." (PMID 28660889, 2017). "Defects in MYO7A are cause of syndromic (USH1B) and nonsyndromic deafness (two form of dominant (DFNA11) and recessive (DFNB2) deafness)." (PMID 28451532, 2017).
deafness (continued). "Among a number of nonsyndromic deafness genes, variants in SLC26A4, COCH, MYO7A, GRHL2, and CLIC5 as well as POU4F3 are known to cause vestibular symptoms and/or dysfunction." (PMID 28545070, 2017). "It is notable that the paralogs PDZD7, USH1C, and DFNB31 are all deafness genes and interact with MYO7A." (PMID 27525485, 2016). "The most frequent causative gene revealed by this technology was CDH23 (n = 3), followed by MYO15A (n = 2), MYO7A (n = 2) and other four deafness genes (PCDH15 (n = 1), USH2A (n = 1), MYO3A (n = 1) and ACTG1 (n = 1))." (PMID 25373420, 2014). "There were also three probands (SHJ3, SHJ16, and SNUH53-118) with only one definitely pathogenic mutant allele in one of three recessive deafness genes, OTOA, MYO15A, and MYO7A, respectively." (PMID 25373420, 2014). "By pursuing the same activity experiment, another mutation p.R244P in the head motor of MYO7A was also found to seriously destroy the function of myosin VIIA, which further explained the genotype and phenotype in mutations of MYO7A and deafness." (PMID 23383098, 2013). "Mutations in nine deafness genes (COCH, KCNQ4, MYO7A, TECTA, CRYM, POU3F4, EYA1, mitochondrial tRNA(Lys) m.8296A>G, mitochondrial tRNA(Ser) m.7445A>G) were not identified in any patients." (PMID 22384008, 2012). "Notably, in both D. melanogaster and vertebrate auditory structures, Zip/MYH9 and Ck/MYO7A genetically and physically interact, and mutations in both MYH9 and MYO7A are associated with deafness in humans." (PMID 40700419, 2025). "For instance, gene replacement strategies for OTOF variations have reached the stage of clinical trials, and preclinical studies have demonstrated the potential of gene editing, antisense oligonucleotides, and RNA-based therapies for other genes associated with deafness, such as GJB2 and MYO7A." (PMID 41227304, 2025). "By contrast, mutations causing complete or near‐complete absence of Myo7a, such as Myo7a4626SB/4626SB, result in early defective hair bundle development and profound deafness." (PMID 41076655, 2025). "In mice, MYO7A knockouts show head shaking, deafness, retinal defects, and reduced male fertility." (PMID 33955556, 2021). "We have identified MYO7A as a possible key deafness gene among indigenous sub-Saharan Africans." (PMID 33671976, 2021). "Overall, 51 mutations correspond to rare genetic deafness/deafness, 5 for US, 2 for US2, 1 for visual and hearing impairment, 16 as retinal dystrophy, 7 for MYO7A-related disorders, 3 for retinitis pigmentosa, 1 each for Amyloidosis, Inborn genetic diseases, and Pigmentary retinopathy." (PMID 33889793, 2021). "Lastly, the significance of the two MYO7A isoforms for human deafness remains to be shown." (PMID 32350269, 2020). "Mutations in non-muscle myosins MYH9, MYH14 and myosin VIIa have been implicated in deafness in mammals." (PMID 21888654, 2011). "The most frequent causative deafness gene was TMC1 (DFNA36) (3 cases), followed by the next tier of genes (2 cases each) (CDH23, COCH, SLC26A4, TMPRSS3, ATP1A3), and the genes that were detected only once (ACTG1, GJB2, ILDR1, MYO7A, MYO15A, NF2, NLRP3 and SERPNB6)." (PMID 32238869, 2020). "Twelve homozygous mutations in known deafness genes, of which eight are novel, were identified in 12 families: MYO15A-p.Q1425X, -p.S1481P, -p.A1551D; LOXHD1-p.R1494X, -p.E955X; GIPC3-p.H170N; ILDR1-p.Q274X; MYO7A-p.G2163S; TECTA-p.Y1737C; TMC1-p.S530X; TMPRSS3-p.F13Lfs*10; TRIOBP-p.R785Sfs*50." (PMID 23226338, 2012). "Disruption of the interactions involving Myo7a MF2 would be predicted to interfere with the formation of strong stereocilia linkages, resulting in deafness." (PMID 28660889, 2017). "In USH1B, absence of functional myosin VIIA results in disorganized hair bundles and disrupted function, leading to profound hearing loss or deafness at birth and balance deficits throughout life." (PMID 36723965, 2023).
deafness (continued). "The most prevalent deafness genes identified in our cohort include SLC26A4 (22%), GJB2 (13%), MYO15A (6%), and OTOF (6%); whereas those identified in the American patients were GJB2 (36%), SLC26A4 (13%), MYO7A (8%), and MYO15A (8%)." (PMID 36009393, 2022). "With regard to the responsible gene, the most frequent causative gene was GJB2 (29%), followed by SLC26A4 (9%), CDH23 (7%), MYO7A (4%), OTOF (5%), MYO15A (3%), and LOXHD1 (2%), indicating that these deafness genes are typical deafness genes found in the prelingual CI/EAS patients." (PMID 32027099, 2020). "In addition, mutations in MYO7A, USH1C, DFNB31, CIB2, CDH23 and PCDH15 were also reported in non-syndromic deafness without retinal degeneration and mutations in USH2A and CLRN1 have been reported in patients with isolated RP or retinal dystrophies and no deafness." (PMID 25211151, 2014). "The Myo7aF947I/F947I dumbo strain is therefore the first reported Myo7a mouse model without an overt vestibular phenotype; a possible model for human DFNB2 deafness." (PMID 23251483, 2012).
hearing loss (60 papers, 2005 to 2026). "In general, autosomal dominant MYO7A-associated hearing loss shows progressive high-frequency, sloping hearing loss." (PMID 41898848, 2026). "For instance, pathogenic variants in the MYO7A gene (USH1B) were generally associated with more severe hearing impairment and earlier onset of retinal dystrophy, if compared to other USH genes-related forms." (PMID 40149483, 2025). "MYO7A holds the distinction of being the first gene discovered to cause hereditary hearing loss in humans." (PMID 41076655, 2025). "Studies of iPSCs from MYO15A and MYO7A mutation patients demonstrate the feasibility of generating inner ear hair cells from human iPSCs and the functional rescue of gene mutation-caused hearing loss by using genetic correction." (PMID 38167128, 2024). "As a result, 137 patients were identified with MYO7A-associated hearing loss so that the prevalence among Japanese hearing loss patients was 1.36%." (PMID 38594301, 2024). "This large cohort study of hearing loss patients provided valuable new insights, particularly with regard to hearing deterioration in MYO7A-associated ADNSHL patients." (PMID 38594301, 2024). "To confirm the protective effect of FK506 against moderate-noise-induced hearing loss, we counted the number of OHCs on surface preparations labeled with Myosin-VIIa and stained with DAB." (PMID 33777956, 2021). "Myosin genes are known to be responsible for 10 types of syndromic as well as non‐syndromic hearing loss (MYO7A, DFNA11/DFNB2/USH1B; MYH9, DFNA17; MYH14, DFNA4; MYO6, DFNA22/DFNB37, MYO3A, DFNB30; MYO15A, DFNB3)." (PMID 32027099, 2020). "Along with these homozygous mutations, we detected two heterozygous variants in well described hearing loss genes (MYO7A and MYH14)." (PMID 31898538, 2020). "The MYO7A variants also accounted for a significant proportion (5.5%) of severe-to-profound hearing loss in our Vietnamese population, which was higher than the estimates found in other studies." (PMID 30733538, 2019). "Similar with PCDH15, the difference of syndromic and nonsyndromic hearing loss induced by mutation of MYO7A was visual disorder." (PMID 29692870, 2018). "DFNB2 locus in one Tunisian family with non-syndromic hearing loss was mapped, and up to date mutations in MYO7A in patients with hearing loss from different populations such as China, Tunisia, Pakistan, Taiwan and Iran have been reported." (PMID 28451532, 2017). "We investigated the clinical impact of MYO7A extended splice region variants, located within ±50 bp of exon-intron boundaries, by analyzing a nationwide Chinese cohort of 10,664 undiagnosed individuals with hearing loss." (PMID 41852313, 2026). "Patients P7 and P8 with MYO7A had severe congenital hearing loss, could articulate, and wore hearing aids, suggesting some useful hearing, which is not typical in USH1B." (PMID 32795431, 2021). "Here, we identified compound heterozygous missense variants MYO7A:p.[Phe456Phe]; p.[Met708Val] and a homozygous variant, p.(Gly163Arg), in two Iranian families with nonsyndromic hearing loss which are affecting the myosin head‐like domain containing residues 1 to 729 of the protein." (PMID 32864763, 2020). "Investigators hypothesize that reduced levels of estrogen and MYO7A are responsible for the hearing loss observed in post-menopausal women." (PMID 31824252, 2019). "Syndromic and non-syndromic hearing impairment are caused by mutation within MYO7A in humans." (PMID 30881389, 2019). "Mutation frequency of MYO7A gene in different populations of Iran as well as cause of hearing loss in most cases are still unknown and more extensive studies have to be done." (PMID 28451532, 2017). "In addition, sequencing of all MYO7A exons in 60 families with hereditary hearing loss, led to the identification of further mutations in SF42 family." (PMID 28472130, 2017). "It is the first time that MYO7A mutations are identified with hearing loss in Morocco." (PMID 28472130, 2017).
hearing loss (continued). "However, the prevalence and detailed clinical features of MYO7A-associated hearing loss across a large population remain unclear." (PMID 38594301, 2024). "(2025) represents a significant milestone in this context, successfully expanding this therapeutic repertoire by treating myosin VIIa (MYO7A)‐related hearing impairment in the Shaker‐1 (Myo7ash1/sh1) mouse model." (PMID 41076655, 2025). "Two genes encoding conventional myosins, MYH9 and MYH14, and four genes encoding unconventional myosins, MYO3A, MYO6, MYO7A and MYO15A, are associated with nonsyndromic hereditary hearing loss in human." (PMID 38562617, 2024). "There are several papers reporting NGS analysis results for hearing loss patients; however, many of them pre-screened GJB2- or SLC26A4-associated HL cases, making it difficult to estimate the true prevalence of MYO7A-associated HL." (PMID 38594301, 2024). "It is also not known whether the efferent reinnervation of adult IHCs of Myo7a-deficient mice can be undone and reverted to its normal configuration by reinstating normal IHC function, which may have implications for future therapeutic intervention aimed at treating age-related hearing loss." (PMID 39641274, 2024). "Consistently, a similar type of hearing loss has also been associated with many variants in TECTA, MYO7A, HGF, and POU3F4 in previous reports." (PMID 33976695, 2021). "Compared to the prelingual group, many genes with autosomal dominant inheritance, such as MYO7A, ACTG1, DFNA5, MYO6, and CRYM, as well as mitochondrial genes reported to cause progressive hearing loss, were found to be involved." (PMID 32027099, 2020). "In this study, only three causative genes, MYO7A, CDH23 and USH2A with novel and known variants contributed to both RP and hearing loss." (PMID 31850270, 2019). "This type of hearing loss is uncommon and has been associated with only the DIAPH1, MYO7A and WFS1 genes." (PMID 22938506, 2012). "Mutations in the MYO7A gene are also associated with an autosomal recessive form of non-syndromic hearing loss known as DFNB2, and with an autosomal dominant form of hearing loss designated DFNA11." (PMID 22690115, 2012). "Several variants of the USH1 genes, MYO7A, CDH23, and USH1G, sometimes with digenic inheritance, have been reported to be linked to atypical USH with variable age at onset and severity of the hearing loss and RP." (PMID 35353227, 2022). "Interestingly, the same MYO7A variant c.4921G>A (p.(Glu1461Lys)) is heterozygous in another patient ID18, who has nonsyndromic hearing loss." (PMID 33924653, 2021). "Patients with mutations in MYO7A exhibited a spectrum of phenotypes ranging from USH I to USH III to atypical USH consisting of non-syndromic hearing loss without retinal a phenotype." (PMID 26338283, 2015). "Studies on mutation of gene MYO7A that causes DFNB2, DFNB11 and Usher1B were the first ones to show that one single gene could determine both forms of hearing loss, syndromic and non-syndromic." (PMID 16446920, 2005). "The estimated prevalence of MYO7A-associated hearing loss in the Japanese hearing loss cohort was 1.36% for all patients, 4.06% for ADNSHL among autosomal dominant or maternal inheritance cases, 0.38% for ARNSHL and 0.32% for USH1B among autosomal recessive or sporadic hearing loss cases." (PMID 38594301, 2024). "To assess the protective effect of MDL-28170 against noise-induced hearing loss at the morphological levels, we counted OHC numbers along the entire length of the cochlear spiral after final ABR measurements (2 weeks after noise exposure) and labeling with myosin-VIIa and staining with DAB." (PMID 37484825, 2023). "This is the first such Myo7a mouse mutant not to exhibit such behaviour and may indicate the existence of an undetected or subtle vestibular phenotype in human patients with hearing loss that do not exhibit an obvious balance defect." (PMID 23251483, 2012).
hearing loss (continued). "Variants in MYO7A, USH1C, CDH23, PCDH15, and WHRN are also responsible for non-syndromic hearing loss associated with loci DFNB2 and DFNA11, DFNB18, DFNB12, DFNB23, and DFNB31, respectively." (PMID 38525684, 2024). "In this study, no EYA1, MYO7A, or POU3F4 gene mutations were detected in any of the 717 hearing loss patients." (PMID 27627659, 2016). "Mutations of MYO7A, CDH23, USH1C, PCDH15, USH1G, and WHRN can cause non-syndromic recessive hearing impairment, and MYO7A variants are also associated with a non-syndromic dominant form of hearing impairment." (PMID 35353227, 2022). "Heterozygosity for MYO7A p.T381M has been documented in 3 unrelated patients with nonsyndromic SNHI from Taiwan, and co-segregated with the phenotype of hearing impairment in the pedigree of Family DE3050." (PMID 23451214, 2013).
Usher syndrome type 1 (29 papers, 2010 to 2026). "Our findings demonstrate a statistically significant association between cataract development and MYO7A mutations in patients with Usher syndrome type I, aligning with and extending observations from previous studies." (PMID 40725401, 2025). "The finding of mutation in MYO7A in these families provides evidence of genetic heterogeneity in Hutterites affected by Usher syndrome type I." (PMID 22690115, 2012). "Two variants in MYO7A (NM_000260.3) were identified: c.1344-2A > G (splicing site mutation reported in ClinVar for Usher Syndrome type I, either in homozygous or compound heterozygous state; rs111033415), in trans with the novel nonsense variant c.733C > T, p.(Gln245*)." (PMID 34997062, 2022). "Type I Usher syndrome, the most severe form, is mostly caused by mutations in MYO7A (myosin VIIA; also known as USH1B)." (PMID 25650393, 2015). "Clinical data for MYO7A patients were concordant with type I Usher syndrome." (PMID 34948090, 2021). "Among these proteins, SANS and myosin VIIa are involved in human Usher syndrome type I." (PMID 20502675, 2010). "In addition to MYO7A (DFNA11, DFNB2, and Usher syndrome type I), OTOF (DFNB9), CDH23 (DFNB12 and Usher syndrome type I), and WHRN (DFNB31) are present within the hair cell or its stereocilia." (PMID 37289589, 2023).